PEAK1 (pseudopodium enriched atypical kinase 1)
Description:
Probable catalytically inactive kinase. Scaffolding protein that regulates the cytoskeleton to control cell spreading and migration by modulating focal adhesion dynamics. Acts as a scaffold for mediating EGFR signaling.
Synonyms: KIAA2002; sgk269
Tractability: Small molecule: a high-quality ligand is known; it belongs to a druggable protein family. PROTAC: its protein half-life has been measured; a small molecule that binds it is known.
Target class: Enzyme; Transferase
Gene: Protein-coding gene on chromosome 15 (77,100,656 to 77,420,216, reverse strand). Ensembl gene ENSG00000173517.
Subcellular location: Cytoplasm, cytoskeleton; Cell junction, focal adhesion
Subcellular location (Human Protein Atlas): Focal adhesion sites; Cytosol
Pathways (Reactome):
Signal Transduction: RHOU GTPase cycle; RHOV GTPase cycle
Gene Ontology:
Molecular function: ATP binding; identical protein binding; non-membrane spanning protein tyrosine kinase activity; protein binding; protein kinase activity
Biological process: cell migration; focal adhesion assembly; protein autophosphorylation; regulation of focal adhesion assembly; substrate adhesion-dependent cell spreading; regulation of cell motility
Cellular component: actin cytoskeleton; focal adhesion; cytoskeleton
Genetic constraint (gnomAD): Loss-of-function variants: 54 observed, 129.75 expected, observed/expected ratio (o/e) 0.42, 90% interval 0.33 to 0.52. The upper end of that interval is the gene's LOEUF score, 0.52, which puts it in group 2 of 6, group 1 being the genes least tolerant of losing a copy. Missense variants: 2,045 observed, 2,249.7 expected, observed/expected ratio (o/e) 0.91, 90% interval 0.88 to 0.94. Synonymous variants: 719 observed, 805.54 expected, observed/expected ratio (o/e) 0.89, 90% interval 0.84 to 0.95.
Homologues: Orthologues: chimpanzee PEAK1 (99% identical), macaque PEAK1 (98% identical), pig PEAK1 (92% identical), guinea pig PEAK1 (88% identical), rat Peak1 (86% identical), rabbit PEAK1 (86% identical), mouse Peak1 (86% identical), zebrafish peak1 (50% identical), dog PEAK1 (45% identical), tropical clawed frog peak1 (42% identical). Paralogues in human: PRAG1 (23% identical), PEAK3 (8% identical), PINK1 (8% identical).
Diseases named in the same sentence as PEAK1 in open-access papers:
PEAK1 is named in the same sentence as 35 diseases in open-access papers, as found by Europe PMC text mining. Sharing a sentence is not in itself a finding about the gene and the disease. The quoted sentences say what the papers report.
breast carcinoma (18 papers, 2014 to 2025). "High PEAK1 expression was associated with the invasion, metastasis and chemoresistance of breast cancers." (PMID 34554318, 2022). "In contrast, elevated PEAK1 expression alone across all breast cancer subtypes had a very modest prognostic association with OS or DMFS." (PMID 34239043, 2021). "To this end, we report that PEAK1 expression in breast cancer stroma is associated with relapse in HER2-positive breast cancer and that PEAK1 is predominantly expressed in tumor associated SNAI2-positive fibroblast-like cells." (PMID 34239043, 2021). "In the current study, PEAK1 expression was correlated with lymph node metastasis and Ki-67 expression, further confirming that PEAK1 may be used as a diagnostic marker for breast cancer invasion and prognosis." (PMID 34554318, 2022). "Importantly, increased PEAK1 has been linked to the progression and metastasis of breast cancer." (PMID 34500744, 2021). "Of note, this analysis emphasised the importance of high expression of both PEAK1 and CAMK2D, consistent with a co-activating PEAK1/CAMK2D ‘cassette’ promoting breast cancer progression." (PMID 39984440, 2025). "To gain further insights into the combined role of PEAK1 and CAMK2/G in breast cancer, we interrogated their association with distant metastasis-free survival (DMFS)." (PMID 39984440, 2025). "The finding that CAMK2 and PEAK1 reciprocally regulate led us to interrogate how the expression of these proteins is related to breast cancer patient survival." (PMID 39984440, 2025). "In the present study, the blockade of PEAK1 expression inhibited cell growth, invasion and migration in vitro, and inhibited tumor growth and lung metastasis in vivo, suggesting that PEAK1 is the target gene for breast cancer gene therapy." (PMID 34554318, 2022). "PEAK1 expression was significantly upregulated in 61.6% (69/112) of breast cancer tissues in comparison with 26.4% (9/34) adjacent normal tissues (P = 0.033)." (PMID 34554318, 2022). "We investigated PEAK1 expression in breast cancer and analyzed the relationship with clinicopathological status and chemotherapy resistance." (PMID 34554318, 2022). "In the present study, we examined PEAK1 protein expression in human breast cancer tissues and explored the relationship between PEAK1 expression and clinical characteristics." (PMID 34554318, 2022). "Using immunohistochemical methods, we measured PEAK1 expression in 112 breast cancer cases and 34 cases with corresponding adjacent normal tissues." (PMID 34554318, 2022). "Inhibiting PEAK1 decreased cell growth, invasion, metastasis and reversed chemoresistance to doxorubicin in breast cancer cells both in vitro and in vivo." (PMID 34554318, 2022). "In breast cancer cells in vivo, forced PEAK1 expression can induce new blood vessel formation by upregulating vascular endothelial growth factor receptor-2, which facilitates cell movement and growth." (PMID 34554318, 2022). "In breast cancer, PEAK1 levels correlate with mesenchymal cell gene expression, poor cellular differentiation and disease relapse." (PMID 34554318, 2022). "Previous studies have identified PEAK1 as a positive regulator of cell growth and metastasis in lung cancer, breast cancer and pancreatic cancer." (PMID 34365903, 2021). "Enhanced PEAK1 expression has reported to promote metastasis and tumor growth in pancreatic cancer, breast Cancer, lung cancer and colorectal cancer." (PMID 34365903, 2021). "In breast cancer cells, PEAK1 mediates TGF-β receptor signals and integrin/Src/MAPK pathways and regulates TGF-β-induced epithelial–mesenchymal transition (EMT) and metastasis." (PMID 34365903, 2021). "This analysis demonstrated good cell resolution and lapatinib-induced reduction in breast cancer cell number that was significantly blocked by the presence of PEAK1-expressing MSCs." (PMID 34239043, 2021). "PEAK1 has been found to regulate the responses of transforming growth Factor β in breast cancer models." (PMID 34500744, 2021).
breast carcinoma (continued). "We first examined patient survival across all breast cancer subtypes in relation to PEAK1 expression levels." (PMID 34239043, 2021). "Here, we determined that stromal PEAK1 expression predicts poor outcomes in HER2-positive breast cancers high in SNAI2 expression and enriched for MSC content." (PMID 34239043, 2021). "In this regard, we demonstrate that high PEAK1 expression in HER2-positive breast cancer patient tissues predicts increased disease relapse in HER2-positive breast cancers high in SNAI2 expression and mesenchymal stem cell (MSC) content." (PMID 34239043, 2021). "Using the shScr and shP1 MSC derivatives in this co-culture assay revealed that PEAK1 expression mediates the ability for MSCs to protect neighboring breast cancer cells against lapatinib-induced cytotoxicity." (PMID 34239043, 2021). "In this regard, we identify a new PEAK1-INHBA/activin-A-dependent axis in MSCs that is necessary for MSC-induced lapatinib resistance in HER2-positive breast cancer cells." (PMID 34239043, 2021). "Recently, it was found that AXL and PEAK1 are co-expressed in aggressive basal B breast cancers where AXL is required for invasion." (PMID 32681075, 2020). "It has shown that TGF-β/PEAK1 signaling is participated in breast cancer cells metastasis and EMT14,15." (PMID 30038287, 2018). "Amplified PEAK1 levels were found in colon cancer, pancreatic cancer, and breast cancer, suggesting that it is a potential therapeutic target." (PMID 27916872, 2016). "Recently, studies indicated that PEAK1 acts as a molecular switch that regulates context-dependent TGF-β responses in breast cancer." (PMID 27916872, 2016). "To evaluate the role that PEAK1 plays in TGFβ-induced EMT and metastasis in breast cancer, we proceeded to generate PEAK1-overexpressing MCF7 cells and PEAK1 knockdown MCF10CA1h cells." (PMID 26267863, 2015). "In the current study, we analyzed PEAK1 expression in human breast cancer samples and found PEAK1 levels correlate with mesenchymal gene expression, poor cellular differentiation and disease relapse." (PMID 26267863, 2015). "Analysis of additional markers of EMT revealed that breast cancer samples with high PEAK1 levels expressed reduced levels of the epithelial markers MUC1, E-Cadherin and Entactin and increased levels of the mesenchymal markers Syndecan1 and LEF1." (PMID 26267863, 2015). "At the cellular level, we also observed that PEAK1 expression was highest in mesenchymal breast cancer cells, correlated with migration potential and increased in response to TGFβ-induced epithelial-mesenchymal transition (EMT)." (PMID 26267863, 2015). "Previous breast cancer microarray studies were analyzed for PEAK1 mRNA expression in relation to markers of poor patient prognosis." (PMID 26267863, 2015). "This further understanding of the role of PEAK1 in TGFβ signaling during breast cancer progression should pave the way for the development of targeted therapies to block breast cancer progression and increase patient survival." (PMID 26267863, 2015). "Taken together, these results clearly indicate that TGFβ-induced motility in breast cancer cells is potentiated by fibronectin in a PEAK1-dependent manner." (PMID 26267863, 2015). "Likewise, AXL-mediated NEDD9 phosphorylation is reported to recruit CrkII and thereby PEAK1, leading to altered FA dynamics in breast cancer cells." (PMID 37336884, 2023). "Measuring PEAK1 could be utilized to predict chemoresistance, and targeting PEAK1 could be used for reversing chemoresistance in breast cancer." (PMID 34554318, 2022). "Immunohistochemistry for PEAK1 was performed in 112 surgically resected breast cancer tissues." (PMID 34554318, 2022). "Furthermore, targeting PEAK1 inhibited cell growth and metastasis and reversed chemoresistance in breast cancer cells." (PMID 34554318, 2022). "In conclusion, PEAK1 is overexpressed in breast cancer and chemoresistant breast cancers." (PMID 34554318, 2022).
breast carcinoma (continued). "We also investigated the role of PEAK1 in breast cancer cells in vitro and in vivo." (PMID 34554318, 2022). "PEAK1 may be a useful prognostic biomarker and a potential therapeutic target for patients with breast cancer." (PMID 34554318, 2022). "We investigated the role of PEAK1 in mediating breast cancer cell metastasis in vivo." (PMID 34554318, 2022). "In addition, PEAK1 was overexpressed in 112 cases of breast cancer patients treated with chemotherapy." (PMID 34554318, 2022). "Furthermore, we investigated the effect of PEAK1 on breast cancer cell growth, invasion, migration, metastasis and doxorubicin sensitivity in vitro and in vivo." (PMID 34554318, 2022). "To confirm our observations, we tested PEAK1 expression in 53 cases of breast cancer patients being treated with neoadjuvant chemotherapy treatment and found that PEAK1 expression was significantly enhanced in chemoresistant breast cancer." (PMID 34554318, 2022). "Research has been reported that PEAK1 plays a positive role in regulating cell growth, invasion and metastasis in human lung cancer, colorectal cancer, breast cancer pancreatic ductal adenocarcinoma and therapy resistance in human pancreatic ductal adenocarcinoma." (PMID 34365903, 2021). "Furthermore, mesenchymal stem cells (MSCs) and cancer-associated fibroblasts (CAFs) express high PEAK1 protein levels and potentiate tumorigenesis, lapatinib resistance and metastasis of HER2-positive breast cancer cells in a PEAK1-dependent manner." (PMID 34239043, 2021). "We observed that PEAK1-dependent MSC-induced protection of HER2-positive breast cancer cells against lapatinib could occur in vivo and in vitro." (PMID 34239043, 2021). "Notably, we also demonstrate that HER2-positive breast cancers contain fibroblastic stromal cells positive for both cytoplasmic PEAK1 and nuclear SNAI2." (PMID 34239043, 2021). "Single-cell CycIF analysis of MSC-breast cancer cell co-cultures identified enrichment of p-Akthigh/p-gH2AXlow, MCL1high/p-gH2AXlow and GRP78high/VIMhigh breast cancer cell subpopulations by the presence of PEAK1-expressing MSCs and lapatinib treatment." (PMID 34239043, 2021). "Notably, we observed that MSC expression of PEAK1 was required for MSCs to induce metastatic spread of HER2-positive breast cancer cells to the brain in animals treated with lapatinib." (PMID 34239043, 2021). "In addition to the PI3K/Akt cascade, GAS6-induced AXL activation and triggers kinase signaling, including ERK and PEAK1, which contribute to the high invasiveness of breast cancer cells." (PMID 34831142, 2021). "In parallel, we mined data on breast cancer stromal gene expression and discovered that PEAK1 expression was significantly higher in malignant breast stroma, and that elevated stromal PEAK1 expression positively correlated with disease relapse." (PMID 34239043, 2021). "In support of a cooperative role for PEAK1 and SNAI2 within the same fibroblastic stromal cells in HER2-positive breast cancers, the poor prognostic utility of PEAK1 in HER2-positive breast cancer was notably restricted to patient tumors expressing high levels of SNAI2." (PMID 34239043, 2021). "Hence, future work should aim to determine the subtypes of breast cancer that would be candidates to AXL or PEAK1 inhibition to limit metastasis." (PMID 32681075, 2020). "Their study also showed that PEAK1 overexpression could promote the proliferation of MDA‐MB‐435 human breast cancer cells, enhance the activity of ERK kinase, and promote tumor formation in nude mice." (PMID 32167655, 2020). "In addition, PEAK1 overexpression has been found in breast cancer and is involved in the progression and metastasis of breast cancer." (PMID 30038287, 2018). "Thus, PEAK1 can be used to determine when TGF-β blockade is viable in targeted therapy of breast cancer." (PMID 27916872, 2016).
breast carcinoma (continued). "Importantly, these data demonstrate for the first time that the cooperative effects of TGFβ and fibronectin on breast cancer metastasis require PEAK1 kinase expression/function." (PMID 26267863, 2015). "We report here that PEAK1 kinase is a novel molecular regulator of TGFβ signaling responses, and plays a critical role in determining the context in which TGFβ signaling elicits tumor suppressive or pro-tumorigenic functions in breast cancer cells." (PMID 26267863, 2015). "Thus, by targeting PEAK1 protein-protein interactions or the regulators of PEAK1 expression breast cancer cell growth can be significantly reduced and/or cells can be made more sensitive to chemo- or targeted-therapies." (PMID 26267863, 2015). "Furthermore, the fact that PEAK1 knockdown alone does not abrogate the metastatic potential of these cells demonstrates a specific role for PEAK1 in TGFβ-induced metastasis in breast cancer." (PMID 26267863, 2015). "Finally, PEAK1 overexpression/upregulation cooperates with TGFβ to reduce breast cancer sensitivity to Src kinase inhibition." (PMID 26267863, 2015). "We next asked whether PEAK1 expression can influence the EMT response in breast cancer cells when exposed to TGFβ." (PMID 26267863, 2015). "Therefore, PEAK1 could serve as a valuable biomarker for the prediction of breast cancer invasion and could also play an important role in prognosis prediction." (PMID 34554318, 2022). "However, the relationship between PEAK1 expression and clinicopathological status and the relationship between PEAK1 expression and chemosensitivity in breast cancer are currently unknown." (PMID 34554318, 2022). "Here we found that PEAK1 overexpression was correlated with a larger tumor size, higher tumor stage, tumor grade, tumor stage, lymph node metastasis and recurrence, suggesting that PEAK1 overexpression may promote the malignant potential of breast cancer." (PMID 34554318, 2022). "Targeting PEAK1 could be an effective treatment strategy for breast cancer." (PMID 34554318, 2022). "This is consistent with both our observation that HER2-positive breast cancer cells xenografted with MSCs displayed increased expression of αSMA and vascular architecture in a PEAK1-dependent manner and recent work reporting a role for PEAK1 during developmental angiogenesis." (PMID 34239043, 2021). "Interestingly, blood vessels in adjacent tissue also showed PEAK1 immunoreactivity, but it was restricted to the abluminal regions of vessels, while in breast cancer samples, it was highly expressed on the luminal side of vessels, where it strongly co-localized with CD31-positive ECs." (PMID 29872538, 2018). "In addition to functioning as a biomarker, our results suggest that PEAK1 may be a viable target for reversing the cellular response to TGFβ action in more advanced stages of breast cancer." (PMID 26267863, 2015). "The interaction of these CAMK2s with endogenous PEAK1 and PEAK2 was interrogated by proximity ligation assays in MDA-MB-231 breast cancer cells." (PMID 39984440, 2025). "Specifically, we identified that the fibroblastic stroma in HER2-positive breast cancer patient tissue stains positive for both nuclear SNAI2 and cytoplasmic PEAK1." (PMID 34239043, 2021). "Finally, we combine protein array and single-cell CycIF multiplex methods to identify a previously unrecognized PEAK1-INHBA-antiapoptotic stromal-tumor cell signaling axis that may be leveraged to abrogate therapeutic resistance in HER2-positive breast cancer and improve patient outcomes." (PMID 34239043, 2021). "Like PEAK1, elevated SNAI2 expression in HER2-positive breast cancer predicts reduced RFS as well as DMFS in HER2-positive breast cancer – patterns also observed for fibronectin in this same cancer subset." (PMID 34239043, 2021). "Next, we evaluated the effect of PEAK1 overexpression on TGFβ-induced Smad2/3, Src and MAPK signaling in MCF7 breast cancer cells." (PMID 26267863, 2015).